MMP2 (matrix metallopeptidase 2)
Diseases named in the same sentence as MMP2 in open-access papers (continued):
Sharing a sentence is not in itself a finding about the gene and the disease.
breast cancer (continued). "IATL inhibits breast cancer cell adhesion, migration, and invasion via the p38 MAPK/NF-κB signaling pathway, and the activity and expression of MMP-2 and MMP-9 are downregulated by IATL in a dose-dependent manner." (PMID 38111074, 2023). "In ovarian cancer and breast cancer, PGRN increased the invasion of tumor cells by upregulating MMP-2 and MMP-9 proteins." (PMID 37660003, 2023). "In breast cancer, overexpression of CDH3 will increase cell invasion and migration and increase MMP1 and MMP2 expression." (PMID 37151391, 2023). "Breast cancer cells tend to proliferate when ß‐actin, FOXM1, FBXW7, Fascin, eNOS, MMP‐2 and HER2‐receptor are expressed or stimulated." (PMID 37697969, 2023). "There is also a positive correlation between the expression of MMP-2, MMP-9, and MMP-11 and breast cancer prognosis." (PMID 37798646, 2023). "An MMP-2 sensitive peptide, R9, has been introduced between an immunostimulatory molecule (TLR7/8a imidazoquinolone) and AuNPs to prepare breast cancer vaccines." (PMID 37514054, 2023). "By contrast, the downregulation of MMP-2 and MMP-9 expression with the addition of vitamin A was found in various cancer cell lines including breast cancer, lung cancer, glioblastoma, and chondrosarcoma." (PMID 38069361, 2023). "MMP-2, MMP-7, and VEGF-A are the major genes that promote metastasis and angiogenesis in breast cancer cells." (PMID 36770598, 2023). "TGF-β1 phosphorylates p38 MAPK which can induce the expression of MMP-2 and TIMP-2, and increased migration and invasion in breast cancer cells." (PMID 37248432, 2023). "For instance, MMP2 and MMP9 expression levels are restored upon DNA methyltransferase inhibition with 5-aza-2′-deoxycytidine in pancreatic and breast cancer cell lines, respectively." (PMID 38017545, 2023). "Expression levels of ECM degrading proteases MMP2, MMP3, and MMP14 significantly increased in lung fibroblasts exposed to media conditioned by metastatic breast cancer cells as compared to controls." (PMID 37903851, 2023). "TGF-β1 mediates the mRNA and protein levels of MMPs (MMP-2 and MMP-9) and their inhibitors (TIMP-2 and RECK), which plays an essential role of extracellular matrix homeostasis control in breast cancer progression." (PMID 37248432, 2023). "Genistein was reported to downregulate the expression levels of matrix metalloproteinase-2 (MMP-2) in glioblastoma, melanoma, and breast cancer, as well as regulate caspase-3 and p38MAPK pathways in prostate cancer cell lines." (PMID 35956766, 2022). "In the present study, we measured the expression of MMP-2 and MMP-9 in breast cancer patients and determined their correlations with SPHK1 and CERK in local as well as TCGA cohort." (PMID 36309544, 2022). "Localization of RAB40b on VAMP4-positive secretory vesicles mediates the secretion of MMP-2 and MMP-9 from the Golgi to the EC space and was shown to enhance the invasive potential of human breast cancer cells." (PMID 35563790, 2022). "Invading breast cancer cells begin to degrade restrictive extracellular matrix components by expressing matrix metalloproteinases, such as MMP-2 and MMP-9, and similar matrix reconstruction enzymes that lead to widespread breast cancer invasion." (PMID 35208277, 2022). "Orosomucoid 1 (ORM1) upregulates the expression of matrix metalloproteinases (MMP-2 and MMP-9) consequently promoting epirubicin resistance in breast cancer." (PMID 36699376, 2022). "We proved previously that the activation of NK1R stimulated the expression and activities of MMPs like MMP2 and MMP14, involving the migration of glioblastoma, melanoma, and breast cancer cells." (PMID 35013118, 2022). "The expression and activation of the matrix metalloproteinases MMP-2 and MMP-9 are only increased in breast cancer patients, while MMP-2 induces cancer migration." (PMID 35721116, 2022).
breast cancer (continued). "Breast Cancer: curcumin down regulate of NF-jB, AP-1, COX-1, and –2, VEGF, fibroblast growth factor (FGF), cyclin E, IL-6, and –11, TGF-b, MMP-2, MMP-9, and MMP-13, the upregulation of tissue inhibitor of metalloproteinase-1." (PMID 36712505, 2022). "MMPs exist in six different families, in which gelatinases such as MMP-2 and MMP-9 are the essential enzymes in the invasion and dissemination of breast cancer cells." (PMID 35164236, 2022). "The typical EMT phenotypes, down-regulation of E-cadherin and ZO-1, and up-regulation of N-cadherin and MMP2, were found as well in IGSF9-knowdown breast cancer cells with western blot analysis and immunofluorescence assay." (PMID 36088502, 2022). "Studies have shown that the use of DCH reduces MMP2 and MMP9 activity in breast cancer and oral squamous cell carcinoma." (PMID 36408277, 2022). "In conclusion, SY can inhibit MMP2, caspase-3, and P-SRC in MDA-MB-231 cells to inhibit breast cancer and exert an anti-metastatic effect." (PMID 35795285, 2022). "Meanwhile, RUNX2 expression was increased by increasing the expression of vascular endothelial growth factor, matrix metalloproteases (MMP2, MMP9, and MMP13), and bone sialoprotein (BSP) in breast cancer metastatic cells." (PMID 36092942, 2022). "Molecular markers such as MMP-2 and MMP-9 can be utilized as reference indices to guide the diagnosis and treatment of breast cancer." (PMID 35164236, 2022). "Other angiogenic factors such as MMP-2, MMP-9 and IL-6 can also be elevated via the ADRB signaling pathway following stimulation by adrenaline or NA in several breast cancer cell lines." (PMID 35563552, 2022). "In breast cancer, for example, DX-2400 blocked MMP activity and pro-MMP-2 processing on tumor and endothelial cells, and it inhibited angiogenesis and tumor dissemination in the MDA-MB-231 xenograft mice model." (PMID 35163805, 2022). "According to another experiment, TBG can block breast cancer cell mobility through effectively impeding MMP-2 and MMP-9 synthesis, thereby achieving the inhibition of breast cancer cell proliferation and migration." (PMID 36237327, 2022). "The overexpression of SOD2 in breast cancer MCF-7 cells increased the expression of p21 and E-cadherin and decreased the expression of Cyclin D1 and MMP-2, suggesting that SOD2 inhibits the proliferation, migration, and invasion of MCF-7 cells." (PMID 36142828, 2022). "In breast cancer, overexpression of LAP3 down-regulates the phosphorylation of Hsp27 and upregulates the expression of fascin, Akt phosphorylation, and matrix metalloproteinase-2/9(MMP2/9)." (PMID 35404840, 2022). "Flow was also a poor inducer of the metalloprotease genes MMP2 and MMP9 in the breast cancer cell lines evaluated, suggesting that WSS of low magnitude likely plays little role in stimulating breast cancer invasion into extracellular matrices." (PMID 35520391, 2022). "Calycosin treatment decreased the expression of CD147, MMP-2, and MMP-9 transcripts and proteins in BATF-overexpressing breast cancer cells." (PMID 34096887, 2021). "MMP-2 and MMP-9 are highly expressed in malignant tumors and positively correlate with an aggressive malignant phenotype and poor outcome in breast cancer patients." (PMID 33633298, 2021). "Myofibroblasts and adipocytes are major sources of matrix metalloproteinases, for example, MMP-2 and MMP-9, two MMPs receiving attention in research focusing on breast cancer progression." (PMID 34944905, 2021). "RBMS3 negatively regulates the expression of Twsit1 and reduces the level of Matrix metalloproteinase 2 (MMP2) induced by Twist1, thus inhibiting the invasion and metastasis of breast cancer cells." (PMID 34804951, 2021). "LOX, MMP2, MMP3, MMP9, RHOA, VIM gene panel expression monitoring was considered because they are correlated with a more aggressive and invasive phenotype in breast cancer cells." (PMID 33543395, 2021).
breast cancer (continued). "Further, decrease of MMP-2 expression, and an increase of TIMP-1 intensified antiproliferative and anti-invasive effects on a breast cancer cell line." (PMID 35010907, 2021). "S1P induces the expression of MMP2 in endothelial cells, MMP7 in hepatocellular carcinoma cells, and MMP9 in breast cancer cells." (PMID 34262394, 2021). "It has been demonstrated that vasodilator-stimulated phosphoprotein (VASP), MMP2, and MMP9 expression in breast cancer is diminished upon repression of STAT3 phosphorylation." (PMID 34488773, 2021). "Calycosin treatment inhibited epithelial-mesenchymal transition (EMT) of breast cancer cells by significantly increasing E-cadherin levels and decreasing N-cadherin, Vimentin, CD147, MMP-2, and MMP-9 levels through downregulation of BATF and TGFβ1." (PMID 34096887, 2021). "Among different MMPs, MMP-2 (gelatinase-A) and MMP-9 (gelatinase-B) are strongly expressed and correlated with the tumor invasion and metastasis in breast cancer cells." (PMID 34483918, 2021). "RT-qPCR and western blot results showed that calycosin treatment downregulated the mRNA and protein levels of CD147, MMP-2, and MMP-9 in T47D and MCF-7 breast cancer cells." (PMID 34096887, 2021). "Hydrazinocurcumin, another synthetic curcumin derivative, significantly inhibited expression of MMP-2 and -9 by inhibition of the STAT3 signaling pathway as presented in breast cancer cell lines." (PMID 35010907, 2021). "Calycosin treatment downregulated expression levels of EMT- and metastasis-related proteins such as N-cadherin, Vimentin, CD147, MMP-2, and MMP-9 levels in breast cancer cells." (PMID 34096887, 2021). "Our research team has been intensively studying the diagnostic usefulness of MMPs in gynaecological cancers, including MMP-2 and MMP-9 in breast cancer." (PMID 33916127, 2021). "In breast cancer and glioma cells, using in vitro and in vivo methods, treatment with THC resulted in reductions in MMP2 expression and activity." (PMID 33597628, 2021). "Conversely, TGFβ1 treatment decreased E-cadherin levels and increased N-cadherin, Vimentin, CD147, MMP2 and MMP9 expression levels in the breast cancer cells." (PMID 34096887, 2021). "For example, MMP2 inhibition has been shown to sensitize lung cancer cells and MCF7 breast cancer cells to radiation, but to protect human fibroblasts from the same stress." (PMID 34237080, 2021). "Consistent with the observations of the tumor cell lines and xenograft models, the distribution and intensity of GABARAP negatively correlated with MMP2 (P=0.0013) and MMP14 (P=0.019) in breast cancer tissue specimens." (PMID 33591943, 2021). "In fact, a recent paper showed that ST6Gal-II downregulation inhibited cancer progression, cell adhesion and invasion, and suppressed ICAM-1, VCAM-1, CD24, MMP2, MMP9, and CXCR4 expression in breast cancer cells." (PMID 34577144, 2021). "Sera from patients with lung and breast cancer were analyzed by bidimensional zymography to detect the activity of MMP-9 and MMP-2." (PMID 35723387, 2021). "Western blotting was used to detect the expression of E-cadherin, N-cadherin, vimentin, MMP2 and MMP14 in different functional models of breast cancer subtypes to verify the occurrence of EMT." (PMID 33591943, 2021). "The ERα/β-mediated miR-10b and miR-145 increased MMP2, 7 and 9 expression following overexpression and inhibition, respectively, in ERβ-suppressed MDA-MB-231 breast cancer cells which resulted in increased ERK1/2 activation and aggressive phenotype." (PMID 33809973, 2021). "Zymographic detection of MMP-2 and MMP-9 was observed in breast cancer sera as early as 2004, but it is very likely that the increase attributed to MMP-2 at that time was actually that of the 65 kDa MMP-9." (PMID 35723387, 2021).
breast cancer (continued). "Our results demonstrated that TGFβ1 treatment increased in vitro migration and invasiveness of breast cancer cells by inducing EMT and increasing the expression of pro-metastatic proteins such as CD147, MMP2, and MMP9." (PMID 34096887, 2021). "In the present study, three EMT-related proteins E-cad, N-cad, and vimentin and two proteolytic enzymes MMP-2 and MMP-9 were selected as targets to investigate the influence of SA in the indicated breast cancer cells." (PMID 33381039, 2020). "Studies have shown that increased expression of P2 × 7 receptor can increase the expression of MMP-2 and MMP-9 through NF-kB, ERK1/2 and Akt signals, and promote the migration of prostate cancer and breast cancer cells." (PMID 33330466, 2020). "By MSRE-PCR, we identified abnormal hypermethylation of promoter CpG dinucleotides of five MMP genes, MMP2, MMP23B, MMP24, MMP25, and MMP28, in breast cancer." (PMID 32397602, 2020). "Recent study indicates that disruption of the interaction of Hsp90 and MMP‐2 and MMP‐9 results in metastasis suppression in breast cancer." (PMID 32180962, 2020). "Among them, the metalloproteinases MMP2 and MMP9 that play a key role in the degradation of type IV collagen are overexpressed in breast cancer and correlate with poor prognosis of patients." (PMID 32226772, 2020). "Blocking of the interaction of HSP90 and MMP-2 and MMP-9 induces metastasis suppression in breast cancer and lung cancer, respectively." (PMID 32961679, 2020). "Separate from GLI1, we observed tGLI1-mediated upregulation of matrix metalloproteinase-2 (MMP-2) and MMP-9 which facilitate breast cancer invasion through degradation of the extracellular matrix." (PMID 32957513, 2020). "MMP-2 or (and) MMP-9 was downregulated in breast cancer, osteosarcoma, and renal carcinoma cells with the silence of HMGN5." (PMID 32596388, 2020). "Especially in breast cancer, increased amounts of Fibronectin activate the FAK/ILK/ERK/PIK/NK-κB signaling pathway and hereby mediate an up-regulation of MMP-2 and -9." (PMID 32560557, 2020). "ASCs-derived leptin promoted tumor growth and metastasis of estrogen receptor-positive breast cancer by upregulating PAI-1 and MMP-2." (PMID 33371368, 2020). "The combination of brazilin and doxorubicin has also been shown to inhibit metastasis in HER2-positive breast cancer through downregulation of MMP9, MMP2, and Rac1." (PMID 32986377, 2020). "Also, to analyze the gene expression of additional molecules regulated by SETD310,22,29–32 that could potentially explain the differences between the prognostic impact on diverse breast cancer subtypes, we also quantified MMP-2, KLC4, iNOS and eNOS mRNA levels in MCF-7 and MDA-MB-231 cells." (PMID 32042016, 2020). "MMP-2, MMP-9 and MMP-13 are also reported to be overexpressed in breast cancer patients and correlated with more aggressive phenotypes of breast cancer, poor prognosis and decreased life expectancy." (PMID 32586313, 2020). "The main component, matrine, can inhibit MMP-9 and MMP-2 activation in highly metastatic human breast cancer MDA-MB-231 cells, reduce the mRNA expression levels of MMP-9 and MMP-2, and finally inhibiting tumor cell invasion." (PMID 33708106, 2020). "It has been shown that enhanced expression of HSP70 is accompanied with activation of mesenchymal markers N-cadherin, MMP2, SNAIL, and vimentin and promotes metastasis of breast cancer." (PMID 33096691, 2020). "On the contrary there decreased uPA was apparent in breast cancer cells MDA-MB-231 and -468 at 510 mOsmol/kg and decreased MMP-2 production in MDA-MB-468 at both 430 and 510 mOsmol/kg." (PMID 32060379, 2020).
breast cancer (continued). "MMP-2 and MMP-9 secreted by astrocytes are found responsible for facilitating lung and breast cancer brain metastasis progression, presumably by making the EMC more favorable for tumor cells." (PMID 33262947, 2020). "At the same time, the expressions of MMP2 and MMP9 proteins in trinegative breast cancer cells treated with Bicalutamide were significantly decreased, and the expression of AR protein was also significantly decreased." (PMID 32332626, 2020). "Some of them, such as MMP-2, MMP-9 and MMP-14 are overexpressed in breast cancer, inducing collagen degradation and promoting metastasis." (PMID 32984031, 2020). "Further, several studies have demonstrated that STAT3 up-regulates MMP2, MMP7 and MMP9 in breast cancer cell lines, proteins that are heavily associated with EMT." (PMID 32391382, 2020). "To further determine the mechanism of PTTG1-mediated breast cancer cell invasion, we determined the effect of PTTG1 on the regulation of MMP-2 and MMP-9 expression and activity in MDA-MB-231 cells." (PMID 33250768, 2020). "Matrix metalloproteinases (MMPs) such as MMP2, MMP7, and MMP9 are metastasis markers in breast cancer." (PMID 32408199, 2020). "GALNT14 contributes to breast cancer invasion by altering cell proliferation and motility, by altering the expression levels of EMT genes, and by stimulating MMP-2 activity." (PMID 32733355, 2020). "A clear association between the higher mRNA expression level of ENO1, MMP-2 and MMP-9 with a worse prognosis was already detected, suggesting that the elevated ENO1 and MMPs are promising biomarkers for breast cancer." (PMID 31416219, 2019). "Collectively, these results suggest that MMPs are overexpressed in breast cancer tissues, and the upregulated MMP-9 and MMP-2 mRNAs are correlated with a worse prognosis." (PMID 31416219, 2019). "Our results in this study also showed that IL-6 induced MMP2 and MMP9 expression in breast cancer cell and mediated cell migration." (PMID 31409371, 2019). "Here, we investigated the functional relationship, in a cohort of breast cancer patients, between ENO1/MBP-1 expression and MMP-2 and MMP-9 activity levels in both tissues and sera." (PMID 31416219, 2019). "The current study shows that MMP-2 and MMP-9 protein expression was significantly higher in the breast cancer than in the fibroadenoma and also in moderately differentiated breast cancer." (PMID 31839881, 2019). "In the present study, we have demonstrated for the first time that RSF EtOAc extract displayed a remarkable ability to inhibit metastasis via down regulation of MMP-2 and MMP-9 in MDA-MB-231 breast cancer cells." (PMID 31683960, 2019). "FAK and Src contribute to the activation and secretion of MMP-2 and MMP-9, which in turn drive the cell migration and invasion phenotypes observed in in vitro models of mammary cancer cells." (PMID 31671408, 2019). "Oro-A can inhibit migration by suppressing the expression of MMP-2 and MMP-9 on human breast cancer cells." (PMID 30871117, 2019). "Based on these observations, we next examined the role of MMP2 and MMP9 in IL-6-induced breast cancer cell migration." (PMID 31409371, 2019). "Among these kinases, the secretion and activation of MMP-2 and MMP-9 in breast cancer cell lines is dependent on the cytosolic tyrosine kinases Src, and FAK." (PMID 31554180, 2019). "Among the several MMP family members, MMP-2 and MMP-9 were highly expressed in invasive breast cancer cells." (PMID 31068208, 2019). "Further, we found that knockdown RAI14 inhibits the proliferation, migration and invasion of breast cancer cells by regulating cell cycle and EMT through Akt/Cyclin D1, MMP2, MMP9 and ZEB1/E-cadhrin/Vimentin pathway." (PMID 31772666, 2019). "In particular, MMP-2 and MMP-9 degrade type IV collagen and promote the rupture of basal membranes in colorectal, prostate, lung and breast cancers." (PMID 31671408, 2019).